GSDME (gasdermin E)
Diseases named in the same sentence as GSDME in open-access papers (continued):
Sharing a sentence is not in itself a finding about the gene and the disease.
oligodendroglioma (1 paper, 2022). A well-differentiated (WHO grade II), diffusely infiltrating neuroglial tumor, typically located in the cerebral hemispheres. "For example, genes located on chromosome 19q (oligodendroglioma, molecular type: IDH-mutated, 1p/1pq-codeleted) and genes located on 7p (NOD1, GSDME, IL6) could be altered by frequent 7p gains in molecular GBM." (PMID 35741587, 2022).
ovarian tumors (1 paper, 2022). "However, one recent study showed that GSDME expression at the mRNA level is decreased in ovarian tumors compared to healthy tumors." (PMID 36016611, 2022).
Peri-Implantitis (1 paper, 2022). An inflammatory process with loss of supporting bone in the tissues surrounding functioning DENTAL IMPLANTS. "In inflamed gingival tissues of patients with peri-implantitis, caspase-3 and GSDME were increased and activated compared to healthy gingival tissues." (PMID 35462927, 2022).
prostate tumors (1 paper, 2025). "GSDME showed higher correlation with immune cell surface markers in prostate tumors compared to other cancer types, consistent with pan-cancer analyses from TCGA." (PMID 41413917, 2025). "Our analysis of TCGA database revealed strong correlations between GSDME expression and various immune cell types in prostate tumors, particularly T lymphocytes, CD8 + lymphocytes, NK cells, and cytotoxic cells, which are essential for anti-tumor immune responses." (PMID 41413917, 2025). "Consequently, docetaxel preserves the GSDME function, while single-cell sequencing revealed that GSDME can induce immune cell infiltration, thereby influencing the immune microenvironment of prostate tumors and enhancing the efficacy of avelumab." (PMID 41413917, 2025).
renal carcinoma (1 paper, 2024). A carcinoma arising from the epithelium of the renal parenchyma or the renal pelvis. "The increased expression of GSDME and lysosomal activity in renal cancer cells provided strong evidence for the combination of SGI‐1027 and everolimus in the treatment of advanced RCC." (PMID 39119834, 2024). "For further validation, we knocked down GSDME expression in 786‐O and A‐498 cells and found that it increased the resistance of renal cancer cells to the combined toxicity of SGI‐1027 and everolimus." (PMID 39119834, 2024). "The upregulation of GSDME expression and increased lysosomal activity in renal cancer cells provide a therapeutic window for the combination of these two drugs to treat renal cancer." (PMID 39119834, 2024). "The upregulation of GSDME expression and the increase in lysosomal activity in renal cancer cells will create a greater therapeutic window for the combined treatment." (PMID 39119834, 2024). "In this study, we confirmed through in vitro and in vivo experiments that SGI‐1027 combined with everolimus induces LMP and GSDME‐dependent pyroptosis in renal cancer cells." (PMID 39119834, 2024). "We therefore examined the endogenous expression of GSDME in HK‐2 cells and renal cancer cells." (PMID 39119834, 2024). "Therefore, our findings indicate that renal cancer cells exhibit high expression level of GSDME and increased lysosomal activity." (PMID 39119834, 2024). "Interestingly, the combination of SGI‐1027 and everolimus induced cleavage of PARP and GSDME, rather than GSDMD, indicating that their combination induced apoptosis and GSDME‐dependent pyroptosis in renal cancer cells." (PMID 39119834, 2024).
renal cell carcinoma (1 paper, 2024). "A total of 14 normal human renal specimens (7 males and 7 females) were collected from the patients who underwent renal cell carcinoma radical surgery to evaluate the basal expression levels of GSDMD and GSDME in renal tubular epithelial cells." (PMID 38388468, 2024).
Respiratory insufficiency (1 paper, 2021). "CRS was characterized by fever, hypotension, and respiratory insufficiency associated with elevated serum cytokines, which was positively correlated with GSDME expression level." (PMID 34179006, 2021).
Retinal atrophy (1 paper, 2025). A nonspecific term denoting wasting, especially as a result of degeneration, of the retinal pigment epithelium (RPE) and neurosensory retinal cells. "In this study, we revealed that GSDME activation by atRAL triggered photoreceptor ferroptosis and retinal atrophy via mitochondrial damage and oxidative stress." (PMID 41281747, 2025). "We found that both GSDME elimination and MitoTEMPO treatment repressed atRAL-induced photoreceptor ferroptosis and retinal atrophy by inactivating the mitoROS-induced oxidative stress." (PMID 41281747, 2025).
retinal degeneration (1 paper, 2025). Degeneration of the retina. "Herein, it was observed that GSDME deletion ameliorated photoreceptor ferroptosis and retinal degeneration induced by atRAL, thereby suggesting a link between GSDME and photoreceptor ferroptosis." (PMID 41281747, 2025). "This study aimed to clarify that GSDME activation by atRAL contributes to photoreceptor ferroptosis leading to retinal degeneration via regulating the KEAP1/NRF2/HO-1 signaling pathway, and to provide new insights into the treatment of STGD1 and dry AMD." (PMID 41281747, 2025). "Evidently, these results highlight the importance of the GSDME/mitoROS axis in photoreceptor ferroptosis and retinal degeneration induced by atRAL." (PMID 41281747, 2025). "First, GSDME deletion mitigates retinal degeneration in mice with defects in atRAL clearance." (PMID 41281747, 2025).
retinal disease (1 paper, 2021). "GSDME-mediated pyroptosis is increasingly being demonstrated to play a role in cancer, but its involvement in neurodegenerative diseases including retinal diseases is still largely unexplored." (PMID 35047535, 2021). "GSDME may therefore be the link between PCD pathways we have been looking for and provide an explanation for why we have been able to identify both apoptotic and pyroptotic mechanisms in retinal disease." (PMID 35047535, 2021).
retinoblastoma (1 paper, 2024). A malignant tumor that originates in the nuclear layer of the retina. "Downregulation of Gasdermin E (GSDME), a key regulator of pyroptosis, confers retinoblastoma cells resistance to chemotherapy." (PMID 38164167, 2024).
sarcopenia (1 paper, 2023). Progressive decline in muscle mass due to aging which results in decreased functional capacity of muscles. "Although our results suggested that inhibiting pyroptosis partially improves sarcopenia, we cannot completely negate the pathogenic role of GSDME-mediated pyroptosis in sarcopenia." (PMID 36823174, 2023). "Evidence of GSDME-mediated pyroptosis and activation of apoptotic caspase-8/-3 were also found in skeletal muscle cells of aged mice with sarcopenia." (PMID 36823174, 2023). "Our study highlights the pathophysiological role of pyroptosis mediated by TNF-ɑ/caspase-8/caspae-3/GSDME signaling in the development of sarcopenia." (PMID 36823174, 2023). "Taken together, our data indicated that GSDME-mediated pyroptosis contributes to TNF-α-induced sarcopenia." (PMID 36823174, 2023). "Our work reveals a novel mechanism that TNF-ɑ/caspase-8/caspase-3/GSDME signaling-mediated pyroptosis contributes to the development of sarcopenia." (PMID 36823174, 2023). "It appears that caspase-3/GSDME signaling-mediated pyroptosis may be a promising therapeutic target for sarcopenia." (PMID 36823174, 2023). "Based on previous in vitro studies on sarcopenia, we then used MHC1 as a marker of the in vitro study of sarcopenia to explored whether TNF-α-induced sarcopenia is attributed to GSDME-mediated pyroptosis." (PMID 36823174, 2023). "Caspase-3/GSDME signaling-mediated pyroptosis may be a promising therapeutic target for sarcopenia." (PMID 36823174, 2023). "Hence, both activated apoptostic signaling and GSDME-mediated pyroptosis may co-participate in the development of sarcopenia." (PMID 36823174, 2023).
skin cancer (1 paper, 2021). "Of note, GSDME levels differ depending on the tumor type: low levels are detected in gastric and skin cancer, high levels in lung cancer, colorectal cancer, neuroblastoma, and melanoma." (PMID 33467668, 2021).
Small Intestinal Tumors (1 paper, 2022). "At the same time, pyroptosis-associated proteins were also detected, showing that QCWZD can prevent the development of small intestinal tumors in the Apcmin/+ model by inhibiting GSDME-mediated pyroptosis." (PMID 35910578, 2022).
status epilepticus (1 paper, 2021). Status epilepticus is defined as a continuous seizure lasting more than 30 min, or two or more seizures without full recovery of consciousness between any of them. "We subsequently established a kainic acid-induced status epilepticus (SE) model in mice and validated the mRNA and protein expression of GSDMD and GSDME, the key molecules of pyroptosis, by quantitative reverse transcription PCR (qRT-PCR) and western blotting (WB)." (PMID 35095728, 2021).
steatosis (1 paper, 2025). Increased lipid within the cytoplasm of cells. "Therefore, H2-rich medium inhibited the expression of inflammatory cytokines, and targeted GSDMD and GSDME to alleviate OA-induced steatosis in HepG2 cells." (PMID 40860880, 2025).
Stroke (1 paper, 2024). Sudden impairment of blood flow to a part of the brain due to occlusion or rupture of an artery to the brain. "In our study, we identified hypoxanthine as an important metabolite for mediating GSDME-dependent pyroptosis of endothelial cells during stroke, which is associated with Ca2+ overload." (PMID 39346547, 2024). "Further mechanistic studies using endothelial cells, human blood vessel organoids, and stroke mice demonstrated that hypoxanthine-mediated gasdermin E (GSDME)-dependent pyroptosis of endothelial cells occurs through intracellular Ca2+ overload." (PMID 39346547, 2024). "Using human blood vessel organoids, a stroke mouse model, and clinical patient samples, we demonstrated that hypoxanthine-induced BBB breakdown is mediated by GSDME-dependent pyroptosis in endothelial cells, which is associated with Ca2+ overload." (PMID 39346547, 2024). "In our study, we demonstrated that hypoxanthine induces GSDME-dependent pyroptosis in endothelial cells directly rather than through GSDMD activation, providing deeper insight into why hypoxanthine plays a harmful role after stroke." (PMID 39346547, 2024).
tongue squamous cell carcinoma (1 paper, 2025). A squamous cell carcinoma that arises from the tongue. "Studies on tongue squamous cell carcinoma cell lines showed increased reactive oxygen species (ROS) production, caspase-3 activation, and gasdermin E (GSDME) cleavage by docetaxel (this chemotherapeutic agent promotes apoptosis via the ROS/caspase-3/GSDME pathway)." (PMID 40864763, 2025).
ulcerative colitis (1 paper, 2025). An inflammatory bowel disease involving the mucosal surface of the large intestine and rectum. "Gasdermin E (GSDME) is a newly identified pyroptosis executioner and is upregulated in the intestinal epithelial cell (IEC) of ulcerative colitis (UC) patients." (PMID 40103680, 2025).
uterine endometrioid carcinoma (1 paper, 2022). "GSDME and PJVK mutation were related to uterine endometrioid carcinoma and uterine mixed endometrial carcinoma, respectively." (PMID 35164740, 2022).
varicocele (1 paper, 2023). A condition characterized by the dilated tortuous veins of the spermatic cord with a marked left-sided predominance. "We aimed to expand on the results of a previous study in which pyroptosis-related factor (GSDME) and HSP 90 were accumulated in bilateral varicocele group." (PMID 36819092, 2023). "RIPK1, RIPK3, GSDME and HSP 90 were increased in bilateral varicocele group." (PMID 36819092, 2023).
Yersinia pseudotuberculosis infection (1 paper, 2022). "In the process of Yersinia pseudotuberculosis infection, GSDME and likely itself in neutrophils mostly contribute to IL-1β release." (PMID 36182937, 2022).
tumor (443 papers, 2012 to 2026). "Firstly, there is the remodeling of the immune microenvironment; single-cell sequencing studies have revealed a specific overexpression of GSDME in tumor-associated macrophages (TAMs)." (PMID 40568597, 2025). "Gasdermin E (GSDME) has been found to act as a tumor suppressor, as its genetic loss was associated with reduced antitumor T-cell immunity and poor tumor control in mice." (PMID 40345706, 2025). "In particular, the presence of macrophages caused the reduction of GSDME-dependent pyroptosis, which was proved to play an important role in activation of anti-tumor immunity, induced by CAP." (PMID 41145470, 2025). "In most human cancer cell lines, GSDME is epigenetically suppressed by promoter DNA methylation, and the majority of tumor‐associated GSDME mutations studied impair its ability to induce pyroptosis." (PMID 40783818, 2025). "Nevertheless, the exact molecular mechanism underlying the tumor growth suppression effect following GSDME knockout remains to be fully elucidated." (PMID 40568597, 2025). "GSDME expression enhances phagocytosis of tumor cells by tumor-associated macrophages and increases the number and function of tumor-infiltrating NK and CD8+ T lymphocytes." (PMID 39917567, 2025). "When Caspase-3 cleaves gasdermin E (GSDME)—the product of a tumor-suppressor gene—its N-terminal fragment forms membrane pores, causing cellular swelling and rupture; conversely, low GSDME expression leads to classical apoptosis." (PMID 41459066, 2025). "The expression of GSDME enhanced the phagocytosis of tumor-associated macrophages and the number and function of tumor-infiltrating NK cells and CD8+ T lymphocytes." (PMID 40698137, 2025). "While the precise mechanisms underlying GSDME’s tumor-promoting function in HCC remain incompletely characterized, accumulating evidence implicates two key pathways as central to this oncogenic process." (PMID 40568597, 2025). "Related studies have shown that the phagocytosis of tumor-associated macrophages was enhanced by inducing pyroptosis of GSDME in tumors." (PMID 40698137, 2025). "GSDME expression is accompanied by intensified phagocytosis of tumor cells by tumor-associated macrophages, and the number and function of tumor-infiltrating NK cells and CD8+ T cells also increase." (PMID 40721578, 2025). "Meanwhile, GSDME expression decreased with tumor stages and was associated with longer overall survival (OS) and recurrence-free survival (RFS) in patients with CRC." (PMID 38853246, 2024). "Consistent with this, acquired resistance to BRAFi + MEKi was shown to be dependent on loss of GSDME cleavage, which correlates to a decrease in T cell infiltration in the tumor." (PMID 38391959, 2024). "At the same time, Judy Lieberman's team showed similar results: the cell-killing enzyme Granzyme B can directly cleave GSDME, causing pyroptosis of cancer cells, further activating the anti-tumor immune response and inhibiting tumor growth." (PMID 38323315, 2024). "Studies have shown that GSDME expression promotes the phagocytosis of tumor cells by tumor-associated macrophages and enhances both the quantity and functionality of tumor-infiltrating natural killer cells and CD8+ T lymphocytes." (PMID 38877579, 2024). "It has been confirmed that 5-FU can regulate tumor progression by promoting gasdermin E (GSDME, encoded by DFNA5) cleavage to induce pyroptosis." (PMID 38902235, 2024). "Of note, GSDME is silenced and mutated in multiple tumors, underscoring its essential role in tumor suppression." (PMID 36742298, 2023). "Cancer cells have developed two strategies to evade GSDME-mediated tumor suppression: epigenetic suppression and mutation of GSDME." (PMID 37965452, 2023). "Specifically, wild-type GSDME expression enhances phagocytosis by tumor-associated macrophages (TAMs) and promotes increased infiltration of immune cells, including CD8+ T cells and NK cells." (PMID 38066523, 2023).
tumor (continued). "GSDME can be also cleaved by granzyme B, therefore enhancing the phagocytosis of tumor cells by tumor-associated macrophages, as well as tumor-infiltrating natural killer and CD8+ T lymphocytes." (PMID 37134086, 2023). "Tumor cell death caused by GSDME activation can also be induced by chimeric antigen receptor T (CAR-T) cells." (PMID 37771587, 2023). "NK and CD8+ cytotoxic T cells can deliver GzmB to tumor cells, which induces apoptosis upon activation of caspase-3 and downstream activation of GSDME, which causes pyroptosis." (PMID 37771587, 2023). "GSDMB and GSDME, which have been reported to be associated with anti-tumor immunity in human cancer." (PMID 36068291, 2022). "Fewer fractions of tumor-infiltrating lymphocytes and tumor-associated macrophages were detected in the tumor microenvironment when GSDME was knocked out in mice." (PMID 36457716, 2022). "At the onset of apoptosis, caspase-3 proteolytically cleaves GSDME, which is strongly implicated in tumor suppression." (PMID 35795683, 2022). "Chemotherapy can induce caspase-3-mediated cleavage of GSDME, and form N-GSDME terminal, which can cause pyroptosis of tumor cells." (PMID 36138348, 2022). "Recent studies have shown that CAR-T cells can quickly causes pyrolysis in targeted tumor cells via GZMB/GSDME/CASP3 pathway." (PMID 35725836, 2022). "Caspase-3 after chemotherapeutic drug activation cleaves human GSDME at position 270 amino acid residue to produce GSDME-NT in tumor cells with high GSDME expression, which causes pyroptosis instead of apoptosis." (PMID 36523974, 2022). "In non-neuroendocrine lung cancer cells treated with etoposide, loss of YAP increases GSDME expression levels, switches the cell death route from apoptosis to pyroptosis, and sensitizes tumor cells to etoposide." (PMID 35990696, 2022). "Unfortunately, studies have shown that the expression of GSDME is more abundant in normal tissues, such as the brain, heart, and kidneys, than in tumor cells; thus, these drugs can cause harm to normal tissues." (PMID 36612023, 2022). "According to a pan-cancer analysis, GSDME expression was significantly associated with the survival prognosis of tumor patients." (PMID 35462927, 2022). "Yet, the majority of the mutations in the gene coding for GSDME found in tumor tissues corresponds to the loss of functions mutations, suggesting a tumor suppressor role." (PMID 34490126, 2021). "GSDME (also known as DFNA5) was identified as the causative gene for nonsyndromic hearing loss and has been considered as a tumor suppressor." (PMID 33406603, 2021). "The GSDME gene is frequently silenced in cancer cells, and loss of function (LOF) of GSDME by mutations or hypermethylation of promoter region in cancer cells will significantly reduce the anti-tumor innate immune responses." (PMID 34421915, 2021). "We found a positively correlated of GSDME expression with the estimated infiltration value of tumor-associated fibroblasts for BLCA, CHOL, KIRC, LIHC, STAD, and UCEC, and found a negative correlation for GBM and MESO." (PMID 34381728, 2021). "They found CAR-T cells release granzyme B into tumor cells to activate caspase 3, causing the subsequent activation of GSDME and pyroptosis." (PMID 33504767, 2021). "In GSDME-expressing tumor cells, the damage-associated molecular patterns (DAMPs) generated by the pyroptosis of the cells can recruit immune cells to the tumor microenvironment and enhance their immunity." (PMID 34381721, 2021). "Analysis of immune cell infiltrates underlined the importance of GSDME expression in promoting anti-tumor immune responses characterized notably by tumor-infiltrating NK and CD8+ cytotoxic T cells." (PMID 34490126, 2021). "BRAFi + MEKi trigger the activation of caspase-3, causing the cleavage of GSDME, which is a hallmark of pyroptosis of tumor cells and is essential for T-cell activation and tumor regression." (PMID 34568046, 2021).